GRB7 (growth factor receptor bound protein 7)
Diseases named in the same sentence as GRB7 in open-access papers (continued):
Sharing a sentence is not in itself a finding about the gene and the disease.
oesophageal adenocarcinoma (3 papers, 2020 to 2023). "In oesophageal adenocarcinoma, it has been demonstrated that reducing GRB7 leads to a decrease in proliferation and clonogenic survival, as well as the induction of cell apoptosis." (PMID 38129809, 2023). "Aberrant expression of GRB7 has been investigated in a variety of cancers, such as oesophageal adenocarcinoma, thyroid cancer, colorectal cancer." (PMID 38129809, 2023).
thyroid cancer (3 papers, 2023 to 2024). "GRB7 also modulated the proliferation, cell cycle, migration and invasion of bladder and thyroid cancer via the AKT pathway and GRB7/ERK/FOXM1 signaling cascade." (PMID 39204147, 2024).
gastric adenocarcinoma (2 papers, 2014 to 2024). "Analysis of data from GEPIA database revealed a significant upregulation of GRB7 in gastric adenocarcinoma tissues compared with that in normal gastric mucosal tissues (p < 0.05)." (PMID 39360313, 2024).
gastric tumor (2 papers, 2020 to 2022). "GRB7 in gastric tumor tissue was significantly higher than that in matched tissue from the same patient (33 pairs)." (PMID 36686796, 2022).
lung carcinoma (2 papers, 2022 to 2024). "It was observed that GRB7 proteomic expression showed a significant upregulation in COAD, PAAD, lung cancer, and UCEC samples, while a decrease was noted in KIRC (p<0.001)." (PMID 39742197, 2024).
lymph node metastasis (2 papers, 2015 to 2020). "In esophageal and pancreatic carcinomas, GRB7 was positively correlated with the presence of lymph node metastases." (PMID 32595827, 2020). "Univariate analysis revealed that the level of GRB7 expression, histology (well or moderate/poor), and the presence of lymph node metastasis were significantly correlated with prognosis." (PMID 26465158, 2015).
melanoma (2 papers, 2022 to 2025). A malignant, usually aggressive tumor composed of atypical, neoplastic melanocytes. "We further identified several melanoma-decreased genes uniquely up-regulated by ZDL, including growth factor receptor bound protein 7 (GRB7), neuronal guanine nucleotide exchange factor (NGEF), fatty acid amide hydrolase 2 (FAAH2), and ephrin A3 (EFNA3)." (PMID 40141086, 2025).
metastatic cancer (2 papers, 2019 to 2026). A carcinoma which has spread from the original site of growth to another anatomic site. "On the other hand, tyrosine phosphorylation of Grb7 can also be detected when Grb7 binds to HS-1-associated protein X-1 (HAX-1), a cytoskeletal-associated protein that is overexpressed in metastatic cancers, suggesting the potential role of tyrosine phosphorylation of Grb7 in cancer development." (PMID 31083325, 2019).
Obesity (2 papers, 2023 to 2024). Accumulation of substantial excess body fat. "BMP3 is associated with preadipocyte proliferation, FAM153A is a yet-to-be characterized protein of human adipocytes, and GRB7 is associated with human obesity." (PMID 38069028, 2023).
prostate carcinoma (2 papers, 2017 to 2023). A carcinoma that arises from epithelial cells of the prostate gland. "In addition, we explored therapeutic targets by investigating FOXA1 interacting protein within proteins encoded by upregulated genes in FOXA1 mutant prostate cancer, and identified six genes—HSP90AB1, KDM1A, FKBP4, H2BC15, WNT7B, and GRB7." (PMID 37958805, 2023).
adrenocortical carcinoma (1 paper, 2024). "Whereas the expression of GRB7 in adrenocortical carcinoma (ACC), lymphoid neoplasm diffuse large B cell lymphoma (DLBC), mesothelioma (MESO), pancreatic adenocarcinoma (PAAD), and uveal melanoma (UVM) was found to be insignificant in all three databases." (PMID 39742197, 2024).
bladder tumors (1 paper, 2020). "Among the 18 pairs of specimens, GRB7 mRNA was significantly higher in bladder tumors than in adjacent normal tissues (P < 0.001)." (PMID 33162827, 2020).
embryonal carcinoma (1 paper, 2008). A non-seminomatous malignant germ cell tumor characterized by the presence of large germ cells with abundant cytoplasm resembling epithelial cells, geographic necrosis, high mitotic activity, and pseudoglandular and pseudopapillary structures formation. "In fact, GRB7 is approximately 5-fold downregulated in most seminomas as compared to embryonal carcinomas." (PMID 19424485, 2008). "An increased GRB7 gene copy number was also detected in human testicular germ cell tumors, exhibiting a particularly high expression in immature teratoma, embryonal carcinoma, choriocarcinoma and some (but not all) seminoma, in contrast to its rare incidence in normal testicular tissues." (PMID 19424485, 2008).
endometriosis (1 paper, 2024). The growth of functional endometrial tissue in anatomic sites outside the uterine body. "Additionally, our study highlights several potential key genes likely involved in the pathogenesis of endometriosis by altering cell migration, such as DKK1, GRB7, MIEN1, PIK3R1, and KRT19." (PMID 39595577, 2024).
endothelial dysfunction (1 paper, 2023). In vascular diseases, endothelial dysfunction is a systemic pathological state of the endothelium (the inner lining of blood vessels) and can be broadly defined as an imbalance between vasodilating and vasoconstricting substances produced by (or acting on) the endothelium. "Through this signalling pathway, mutations in Grb7 may cause endothelial dysfunction through reduced angiogenetic activity both through changes in intracellular calcium signalling and the VEGF/Akt (PKB)/NO pathway." (PMID 37383439, 2023).
Fibroadenoma (1 paper, 2020). A benign tumor of the breast characterized by the presence of stromal and epithelial elements. "In benign breast diseases, GRB7 expression is present in the myoepithelial cells of the fibroadenoma but not fibrocystic disease." (PMID 32595827, 2020). "Interestingly, about half (53.3%) of the fibroadenoma samples (n = 15; mean age 29.50 ± 11.35 years) expressed GRB7 in the myoepithelial cells, while no GRB7 expression was seen in the fibrocystic changes samples (n = 15; mean age 24.00 ± 8.91 years)." (PMID 32595827, 2020).
fibrocystic disease (1 paper, 2020). "In the current study we report the tissue distribution of GRB7 protein by IHC in normal human tissues, including benign breast diseases." (PMID 32595827, 2020).
gastritis (1 paper, 2024). Inflammation of the stomach. "We further explored the difference in GRB7 expression between H. pylori-positive and -negative gastritis tissues." (PMID 39360313, 2024).
glioma (1 paper, 2022). A benign or malignant brain and spinal cord tumor that arises from glial cells (astrocytes, oligodendrocytes, ependymal cells). "And GRB7 has been identified to promote glioma growth and associated angiogenesis in vivo." (PMID 35790975, 2022).
head and neck squamous cell carcinoma (1 paper, 2024). A squamous cell carcinoma that arises from any of the following anatomic sites: lip and oral cavity, nasal cavity, paranasal sinuses, pharynx, larynx, and salivary glands. "It indicated that GRB7 expression was significantly elevated in BRCA, CHOL, COAD, KIRP, LIHC, LUAD, and THCA (p<1×10-13), CESC, STAD (p<1×10-11), BLCA, ESCA, head and neck squamous cell carcinoma (HNSC), READ, UCEC (p<1×10-9), and LUSC (p<1×10-5)." (PMID 39742197, 2024).
invasive ductal carcinoma (1 paper, 2020). "We next examined the GRB7 expression levels and localization within the cell, and correlated these results with clinical factors in the invasive ductal carcinoma (IDC) samples." (PMID 32595827, 2020).
ovarian serous cystadenocarcinoma (1 paper, 2023). A malignant serous cystic epithelial neoplasm arising from the ovary. "The top five interacting genes were selected for analysis, and the results showed that PGAP3, GRB7, STARD3, and PSMD3 had a significant positive correlations with STAT3 in TCGA cancers, such as ovarian serous cystadenocarcinoma (OV)." (PMID 36977736, 2023).
pancreatic adenocarcinoma (1 paper, 2024). "Prognostic analysis revealed that high GRB7 expression was linked to a better prognosis in KIRC and a poorer prognosis in pancreatic adenocarcinoma (PAAD) patients." (PMID 39742197, 2024).
salivary duct carcinoma (1 paper, 2024). An aggressive, high grade adenocarcinoma that arises from the salivary glands. "The amplification of GRB7 and ERBB2 may also be an initial step in the malignant transformation of PA to CXPA (salivary duct carcinoma subtype)." (PMID 39384827, 2024).
testicular germ cell tumor (1 paper, 2024). A germ cell tumor arising from the testis. "Additional analysis performed using the GEPIA database showed that GRB7 expression was significantly elevated in BLCA, CESC, CHOL, COAD, OV, READ, testicular germ cell tumors (TGCT), THCA, thymoma (THYM), UCES, and uterine carcinosarcoma (UCS)." (PMID 39742197, 2024).
cancer (65 papers, 2004 to 2025). A tumor composed of atypical neoplastic, often pleomorphic cells that invade other tissues. "Grb7, a crucial protein associatedwith cancer cell proliferationand migration, is a noteworthy target of interest, particularly inbreast cancer subtypes." (PMID 40698392, 2025). "Our computational analyses implicated that GRB7 knockout in cancer cells would enhance their susceptibility to T cell-mediated cytotoxicity." (PMID 39204147, 2024). "This study aimed to assess the diagnostic and prognostic relevance of GRB7 in a comprehensive pan-cancer analysis." (PMID 39742197, 2024). "Tyrosine kinase-signaling genes, EPHB3, SH3TC2, and GRB7, which are associated with poor disease-free survival and promote cancer progression and invasion, were downregulated by DIM–AHR." (PMID 37834026, 2023). "GRB7 has also been described as being involved in cellular proliferation, migration, and invasion, cancer prognosis, and tumor-associated angiogenesis of a variety of tumors." (PMID 35251475, 2022). "Nr1d1 is another candidate in Eaa11, and the co-activation of Erbb1, Grb7, and Nr1d1 has been linked to breast and other cancers." (PMID 35389339, 2022). "Previous efforts to develop bicyclic peptides targeted to the Grb7 signalling protein implicated in HER2+ve cancer progression have resulted in improved affinity." (PMID 35625882, 2022). "Grb7- or ERBB family/Grb7- mediated signal transduction cascades have been implicated in the promotion of cancer migration." (PMID 31083325, 2019). "It has been shown that overexpression of Grb7 enhances cell migration, while inhibition of Grb7 lowers the migratory potential of cells and is therefore linked with metastatic spread of cancer cells." (PMID 27257138, 2016). "Grb7 is frequently overexpressed in invasive and metastatic human cancers and is implicated in cancer progression via its interaction with the ErbB2 receptor and focal adhesion kinase (FAK) that play critical roles in cell proliferation and migration." (PMID 17894853, 2007). "Grb7 is an especially promising cancer target as the encoding gene maps closely to the ErbB2 gene on human chromosome 17q12 and is found co-amplified and overexpressed in a subset of breast, esophageal and gastric cancers." (PMID 17426702, 2007). "Furthermore, clinical statistics have demonstrated that GRB7 overexpression is associated with cancer recurrence and a worse prognosis in these cancer patients." (PMID 39360313, 2024). "In addition, overexpression of human GRB7 has been linked with progression of many cancer types, with evidence indicating it can affect diverse processes, including cell survival, proliferation, migration and invasion, mainly studied in cancer cell lines." (PMID 39343875, 2024). "Alterations in GRB7 expression have been linked to multiple human cancers." (PMID 39742197, 2024). "Aberrant elevation of GRB7 levels is often associated with the progression of human cancer." (PMID 37443682, 2023). "The overexpression of Grb7 or the coamplification/cooverexpression of Grb7 and members of the ERBB family play essential roles in advanced human cancers and are associated with decreased survival and recurrence of cancers, emphasizing Grb7′s value as a prognostic marker and a therapeutic target." (PMID 31083325, 2019). "Displaying different phosphorylation statuses and regulating distinct downstream targets of Grb7 and Grb7v might cause different effects of Grb7 and Grb7v on cancer functions." (PMID 31083325, 2019). "Furthermore, the growth factor receptor-bound protein 7 (GRB7), a gene tightly linked to c-erbB2 and previously reported coamplified and coexpressed with this gene in several cancer types, was also highly differentially expressed in USPC compared to NEC." (PMID 15785748, 2005).
cancer (continued). "Furthermore, the growth factor receptor-bound protein 7 (GRB7), a gene tightly linked to c-erbB2 and previously reported coamplified and coexpressed with this gene in several cancer types was also highly differentially expressed in USPC compared to OSPC." (PMID 15208622, 2004). "Further analyses of TCGA and GTEx databases showed significant upregulation of GRB7 in various cancers compared to their matched normal controls." (PMID 39204147, 2024). "GRB7 exhibited genetic alterations in multiple cancer types, with amplification being the predominant alteration detected in ESCA, while mutations were notably prevalent in SKCM and UCEC." (PMID 39742197, 2024). "GRB7 is the focus of much research in the domains of molecular biology and cancer biology due to its many roles." (PMID 39742197, 2024). "High GRB7 expression increases the capacity for cancer cells to migrate, invade, and spread via interacting with different kinases and phospholipids." (PMID 39742197, 2024). "We conducted a thorough investigation to investigate the expression of GRB7 in OC using datasets from The Cancer Genome Atlas (TCGA), Genotype-Tissue Expression (GTEx), Cancer Cell Line Encyclopedia (CCLE), and Gene Expression Omnibus (GEO)." (PMID 39204147, 2024). "A similar pattern was observed across cancer grades, as GRB7 expression decreased progressively with advancing grades." (PMID 39742197, 2024). "Patients with cancer were categorized into groups with high and low GRB7 expression levels, and their overall outcomes were analyzed to evaluate the prognostic value of GRB7." (PMID 39742197, 2024). "The overexpression of GRB7 or the co-overexpression of GRB7 and members of the ERBB family play essential roles in advanced human cancers and are associated with decreased survival and recurrence of cancers." (PMID 39204147, 2024). "Data from single-cell RNA sequencing data across multiple cancer types indicated GRB7’s predominant expression in malignant cells." (PMID 39204147, 2024). "This work sought to explore the potential of GRB7 in cancer diagnosis and prognosis by performing a thorough pan-cancer investigation using several bioinformatics methods." (PMID 39742197, 2024). "The strong Grb7 expression we observed in the developing gut epithelium is interesting in view of evidence that GRB7 has an oncogenic role in cancers of the intestinal tract, including those of the oesophagus, stomach and colon." (PMID 39343875, 2024). "Significant findings regarding GRB7 were identified by analyzing genetic alteration data across various cancers using the cBioPortal platform." (PMID 39742197, 2024). "This study highlights that GRB7 was downregulated in KICH, suggesting its potential as a diagnostic biomarker for this cancer." (PMID 39742197, 2024). "It has been reported that GRB7, an important targetable factor, participates in varied physiological and pathological processes in human cancers." (PMID 38129809, 2023). "With respect to genes CDK12 (CRKRS), CWC25 (CCDC49), GRB7, MIEN1 (C17orf37), PNMT and SIRT3, they have been shown to be linked to HER2 receptor and cancer." (PMID 37096121, 2023). "Recently, GRB7 has been studied as a therapeutic target in various cancers, which plays important roles in tumor development of cancers by regulating cell proliferation, apoptosis and cell migration." (PMID 38129809, 2023). "It was observed that tumor cells showed strong expression of GRB7, while para-carcinoma tissue cells presented low IHC staining intensity." (PMID 38129809, 2023). "Numerous other genes such as ESPL1, DOCK8, ARID3A, PFKFB4, ANKZF1, BANP and GRB7 showed elevated expression rates, some of which are known or suspected to be involved in cancer development and/or progression." (PMID 37193047, 2022). "These peptides both continue to serve a useful role for studies of Grb7 inhibition in cancer cell lines and other tumour models and will help to establish the therapeutic potential of Grb7-SH2 inhibitors." (PMID 35625882, 2022).